IL6R (interleukin 6 receptor)
Diseases named in the same sentence as IL6R in open-access papers (continued):
Sharing a sentence is not in itself a finding about the gene and the disease.
Sepsis (36 papers, 2015 to 2026). Sepsis is defined as life-threatening organ dysfunction caused by a dysregulated host response to infection. "During sepsis, IL-6 is produced in response to pathogenic stimuli, and IL-6R is generated by neutrophils." (PMID 39835102, 2024). "Recent similar studies also identified the same protective effect in sepsis, where variants in IL6R were again found to be protective against the development of sepsis, admission to critical care with sepsis, and death with sepsis." (PMID 36801374, 2023). "As the down-regulation of functional IL6R potentially leads to increased risk of infection, analyses of genetic variants related to progression to severe infections (e.g., sepsis) has the potential to be biased." (PMID 36716318, 2023). "Anti-inflammatory drugs, including steroids and anti-IL-6 receptor (IL-6R) or anti-TNFα antibodies can reduce tissue harm but augment the risk of sepsis." (PMID 35937253, 2022). "Sepsis‐mediated endothelial damage increases IL‐6 proliferation that causes soluble IL‐6 to bind to its receptor (IL‐6R), forming the IL‐6/IL‐6R complex." (PMID 33719215, 2021). "In a large, UK cohort (N = 485,825, including 11,643 with sepsis), genetic variation acting as a proxy (or natural experiment) for IL6R blockade was associated with a reduced odds of sepsis (odds ratio (OR) 0.80; 95% confidence interval (CI) 0.66 to 0.96) in MR analyses." (PMID 36716318, 2023). "In the UK Biobank cohort (N = 486,484, including 11,643 with sepsis), IL6R blockade was associated with a decreased risk of our primary outcome, sepsis (odds ratio (OR) = 0.80; 95% confidence interval (CI) 0.66 to 0.96, per unit of natural log-transformed CRP decrease)." (PMID 36716318, 2023). "IL6R blockade is causally associated with reduced incidence of sepsis." (PMID 36716318, 2023). "They conducted their genetic study on a large cohort and concluded that IL6R blockade is causally associated with reduced incidence of sepsis; similar but imprecisely estimated results supported a causal effect also on sepsis-related mortality and critical care admission with sepsis." (PMID 37686271, 2023). "YTHDF2 directly recognizing the m6A modification on IL‐6R can decrease the stability of IL‐6R mRNA, thus mitigating sepsis by inhibiting inflammation." (PMID 40548546, 2025). "This pathway is activated by IL-6/IL-6R (gp130) binding and influences cytokine expression in sepsis." (PMID 39367511, 2024). "Previous research has demonstrated the link between upregulated IL-6/IL6R and a poor prognosis in sepsis." (PMID 38026444, 2023). "We demonstrated that eCIRP released during a late stage of sepsis promoted endotoxin tolerance in macrophages by recognizing interleukin-6 receptor (IL-6R) and activating the STAT3 pathway." (PMID 36471113, 2023). "For our primary outcome—sepsis—we identified a severity-dependent effect, with evidence suggesting that IL6R blockade is increasingly protective with more severe disease." (PMID 36716318, 2023). "Of the 317 sepsis-associated genes regulated by these DEMs, five (HIP1, GJC1, MDM4, IL6R, and ERC1) were designated as hub genes based on their degrees and other centrality measures (degree, betweenness, and closeness) from the significant modules." (PMID 33182754, 2020). "Importantly, two studies showed that the rs12692386 A > G allele of ADAM17 increased the protease expression and shedding of TNF, IL-6R, and CX3CL1, conferring a higher risk of severe disease and shock in sepsis." (PMID 38881671, 2024). "It was reported in the literature that IL6R blockade may improve outcome and decrease mortality in sepsis." (PMID 39407738, 2024). "Focusing on variants within or near the IL6R, it is difficult to completely rule out pleiotropic effects (e.g., these SNPs acting to reduce risk of sepsis by another, unrelated mechanism)." (PMID 36716318, 2023). "We performed IVW MR to investigate the association of IL6R blockade on the odds of infection in the absence of sepsis within UK Biobank." (PMID 36716318, 2023).
Sepsis (continued). "We hypothesised that there may be a role for IL6R blockade in sepsis given the similarities between bacterial sepsis and critical illness in COVID-19." (PMID 36716318, 2023). "We also found evidence that IL6R blockade may be protective in critical illness in respiratory infection, where effect estimates were similar to those seen in sepsis and consistent with the COVID-19 data." (PMID 36716318, 2023). "This suggests that one potential route by which IL6R blockade reduces the odds of severe sepsis is by reducing CRP, although this remains a hypothesis." (PMID 36716318, 2023). "Not only does a focus on variants within or near the IL6R fail to guarantee the absence of complications generated as a result of pleiotropy; most of our estimates relate to protection from the odds of sepsis events." (PMID 36716318, 2023). "Recent finding summarized that NEAT1 could also serve as a ceRNA, which regulates sepsis-induced acute kidney injury by sponging miR-204 to target IL-6R and mediating nuclear factor kappa B (NF-κB) pathway." (PMID 32099901, 2020). "We discovered a link between eCIRP and IL-6R in murine macrophages to promote eCIRP-induced macrophage endotoxin tolerance; this provides a strong premise for studying eCIRP’s role in immune tolerance in patients with sepsis." (PMID 32027619, 2020). "There is evidence across both UK Biobank and FinnGen that the apparent protective effect of functional IL6R blockade increases with increasing severity of illness with potential protective effects on short-term death in sepsis and critical care admission with sepsis." (PMID 36716318, 2023). "We hypothesised that blockade of IL6R could also improve outcomes in sepsis." (PMID 36716318, 2023). "However, it remains uncertain whether YTHDF2 affects HMGB1 release and whether the impact of YTHDF2 on HMGB1 release is connected to the regulation of the IL-6R/JAK2/STAT1 pathway in sepsis." (PMID 38026444, 2023). "Although we should be appropriately sceptical of any novel therapeutics in sepsis, given the failure to identify any successful agents despite 30 years of research, the unique conditions surrounding this work suggest that IL6R blockade may be a useful approach." (PMID 36716318, 2023). "lncRNA HOTAIR promoted the progression of sepsis, by inhibiting monocyte proliferation, while promoting monocyte apoptosis and inflammation response; this was achieved by acting as miR-211 sponge, thereby inducing IL-6R expression in CLP-induced sepsis mice model." (PMID 34055659, 2021). "Moreover, the rs653765 CC genotype in severe sepsis showed a higher ADAM10 level compared to healthy groups, and the rs653765 CC polymorphism had a strong impact on the production of the ADAM10 substrates CX3CL1, IL-6R and TNF-α." (PMID 25888255, 2015). "Given the previous data linking genetic variation in IL6R with trial outcomes of IL6RA, and the biological plausibility of effect, these data support trialling IL6RA in sepsis." (PMID 36716318, 2023). "We also examined the effect of anti-IL-6R antibody on the survival of mice after caecum ligation and puncture (CLP), a widely used sepsis model." (PMID 27146354, 2016). "We found that the severe sepsis patients expressed significantly higher levels of CX3CL1, IL-6R, and TNF-a than the healthy controls." (PMID 25888255, 2015). "Our results indicated that the expression of CX3CL1, IL-6R, TNF-a, IL-1ß and IL-6 were significantly higher in the sepsis patients (subtype) than in the healthy controls." (PMID 25888255, 2015). "The differences in the expression levels of ADAM10 substrates (CX3CL1, IL-6R and TNF-a) and the pro-inflammatory cytokines IL-1ß and IL-6 according to the ADAM10 genotype were analyzed in PBMCs from the sepsis patients and the controls." (PMID 25888255, 2015).
Sepsis (continued). "Our results indicate that YTHDF2 plays an anti-inflammatory role by reducing the release of HMGB1 via inhibition of the IL-6R/JAK2/STAT1 pathway, demonstrating that targeting YTHDF2 may constitute a promising approach to sepsis treatment." (PMID 38026444, 2023). "In summary, these findings demonstrate that YTHDF2 plays an essential role as an inhibitor of inflammation to reduce the release of HMGB1 by inhibiting the IL-6R/JAK2/STAT1 pathway, indicating that YTHDF2 is a novel target for therapeutic interventions in sepsis." (PMID 38026444, 2023). "Our findings demonstrate that YTHDF2 plays an essential role as an inhibitor of inflammation by reducing the release of HMGB1 via inhibition of IL-6R/JAK2/STAT1 signalling, indicating that this pathway may be a novel therapeutic strategy for sepsis." (PMID 38026444, 2023). "Importantly, we found that among the subgroup of patients with severe sepsis, the rs653765 CC genotype carriers expressed significantly higher levels of CX3CL1, IL-6R and TNF-a than the CT/TT carriers." (PMID 25888255, 2015). "Although IL-6 is a useful biomarker and diagnostic indicator of sepsis progression, the administration of anti-IL-6 or anti-IL-6R therapy for the treatment of sepsis has not been studied because IL-6 is an important factor driving immune activation as a host defense against infection." (PMID 34253862, 2021). "Given the ongoing development of therapeutics that target trans-specific IL-6 signalling and therapeutics that target CRP itself, this may represent a future avenue in sepsis therapeutics; however, this does not alter the interpretation of the primary IL6R blockade-related finding here." (PMID 36716318, 2023). "However, in sepsis, global blockage of classic IL6 signaling and trans-signaling via IL6-R Mab application was not beneficial, while only selective inhibition of IL6 trans-signaling was." (PMID 36151360, 2023).
colorectal cancer (33 papers, 2010 to 2026). A primary or metastatic malignant neoplasm that affects the colon or rectum. "Blocking the interaction of IL-6 and IL-6R in colitis-associated colorectal cancer (CAC) by anti-IL-6 receptor antibodies reduced the size and number of tumors in mice, and the effect was mediated by the downregulation of HIF-1α." (PMID 40430040, 2025). "Although the causal relationship between macrophages and IL6R in colorectal cancer cannot be determined at present, this lays the foundation for our next exploration of related mechanisms." (PMID 38961677, 2024). "We compared the differential expression of IL6R in relation to immune genes and immune cells between colorectal cancer and (meta‐analysis) high‐risk cancer." (PMID 38961677, 2024). "Among these pathogenic genes, IL6R may play an important role in inhibiting the development of colorectal cancer." (PMID 38961677, 2024). "Thus, in this study we have examined the possible influence of functional polymorphisms within the IL-6, IL-6R, and gp130 genes in individuals with sporadic colorectal cancer on the occurrence of different types of microsatellite instability." (PMID 39199686, 2024). "RA reduced the risk of colorectal cancer through immune‐mediated inflammation, and IL6R may be a key regulatory gene among them." (PMID 38961677, 2024). "In addition, the results of immune cell infiltration indicate that the expression of IL6R in colorectal cancer was mainly associated with B cells, macrophage M2 and mast cells." (PMID 38961677, 2024). "In addition, we also reported that the IL-6R (48892A>C) genetic polymorphism was associated with prognosis in colorectal cancer patients undergoing cancer vaccination." (PMID 38469154, 2023). "Next, for the purpose of exploring the significance of IL6R on the tumour immune microenvironment by investigating the relationship between IL6R and colorectal cancer immunity." (PMID 38961677, 2024). "Compared to other malignancy, the correlation between IL6R and chemokines and immunostimulators were higher in colorectal cancer." (PMID 38961677, 2024). "We found that the mechanism underlying this evidence would be the tumor–stromal interaction between colorectal cancer cells and macrophages in the tumor budding area via the interleukin-6 receptor/STAT3 signaling pathway." (PMID 38486225, 2024). "The comparison results of Timer analysis further indicated that compared to other malignancy, IL6R had a higher correlation with various immune cells in colorectal cancer." (PMID 38961677, 2024). "IL6R was the gene with the highest correlation among them, and its correlation with immune cells was higher in colorectal cancer than in other malignancy." (PMID 38961677, 2024). "The report showed TAM-secreted IL-6-induced chemoresistance by activating the IL-6R/STAT3/miR-204 pathway in colorectal cancer cells." (PMID 39247822, 2024). "Nonetheless, evidence regarding the anti-tumor effects of tocilizumab on human colorectal carcinoma (CRC) corresponding to IL-6R expression levels remains scarce." (PMID 38256960, 2024). "We also demonstrated that the IL-6R A/C or C/C genotype showed a prolonged OS in colorectal cancer patients who received cancer vaccination." (PMID 38469154, 2023). "miR-451 has also been shown to reduce angiogenesis in colorectal cancer cells by targeting the interleukin – 6 receptor (IL-6R) and to decrease T-cell responses to infection by inhibiting the expression of the regulatory gene, myc." (PMID 32321512, 2020). "IL-6 is also known to act via hypoxia-inducible factor (HIF)-1α to increase VEGF expression and this process has been shown to be inhibited by miR-451 mediated regulation of IL-6R expression in colorectal cancer cells." (PMID 32321512, 2020). "The ability of miR-34a to directly bind to the 3′-UTR of IL-6R has been demonstrated in the context of colorectal cancer." (PMID 31448054, 2019).
colorectal cancer (continued). "An earlier finding showing that the IL-6R/STAT3/ miR-34a feedback loop promoted EMT in colorectal cancer prompted us to investigate the existence of the same feedback loop in HGSC." (PMID 31448054, 2019). "Stimulation of HT29p cells with PMA led to an increase of the sIL-6R concentration in the supernatant, demonstrating that colorectal cancer cells express the IL-6R protein on their membrane, and that it can be shed from the surface." (PMID 26673628, 2015). "Previous study has demonstrated the role of IL-6R/STAT3/miR-34a feedback loop in colorectal cancer invasion and metastasis, and our previous study has shown the relationship between miRNA-34a and Eag1." (PMID 26783521, 2015). "According to the immune infiltration score, IL6R also mediates colorectal cancer through immunity." (PMID 38961677, 2024). "Furthermore, in colorectal cancer Mir34a was shown to constrain carcinogenesis by directly inhibiting an IL-6R/STAT3/Mir34a feedback loop, and its ablation is required to induce IL6-mediated EMT and invasion." (PMID 32541781, 2020). "Several human tumour cell lines have been reported to produce IL-6, and an IL-6/IL-6R autocrine loop has been described in several tumours, including oesophageal carcinoma, multiple myeloma, renal cell carcinoma, and colorectal cancer." (PMID 20823887, 2010). "In colon cancer, in which IL-6R was correlated with the tumor size of the patients, a role of IL-6R in colorectal cancer progression was suggested and its possible roles as a biomarker could be useful in the follow-up disease and as potential targets for the therapy." (PMID 36091805, 2022). "In colorectal cancer (CRC), CPEB3 is involved in the crosstalk between cancer cells and TAMs by targeting IL-6R/STAT3 signalling." (PMID 38987822, 2024). "A recent study explained that increasing levels of interleukin 6 receptor (IL6R) and plasminogen activator inhibitor 1 (PAI1) promote colorectal cancer development, progression, and metastasis and participate in inflammation in mice." (PMID 36417020, 2022). "Four ongoing clinical trials were found, involving tocilizumab, an anti-IL6Rα antibody with favorable results in preclinical studies, and napabucasin, a STAT3 inhibitor that is also under investigation in colorectal cancer." (PMID 34138876, 2021). "We previously reported that IL-6R, STAT3 and miR-34a form a positive feedback-loop, which promotes epithelial to mesenchymal transition (EMT), invasion, and metastasis of colorectal cancer (CRC)." (PMID 26091352, 2015). "In our study, IL6R showed the highest negative correlation with colorectal cancer." (PMID 38961677, 2024). "Similarly, colorectal cancer tumorspheres showed increased mRNA levels of CXCL8 and IL6R." (PMID 39336151, 2024). "However, we did not detect the IL-6R on the surface of colorectal cancer cells by flow cytometry (data not shown)." (PMID 26673628, 2015).